SIGLEC16 (sialic acid binding Ig like lectin 16 (gene/pseudogene))
Description:
Putative adhesion molecule that mediates sialic-acid dependent binding to cells.
Synonyms: SIGLECP16; Siglec-P16
Gene: Protein-coding gene on chromosome 19 (49,969,600 to 49,975,819, forward strand). Ensembl gene ENSG00000161643.
Subcellular location: Membrane
Genetic constraint (gnomAD): Missense variants: 280 observed, 358.51 expected, observed/expected ratio (o/e) 0.78, 90% interval 0.71 to 0.86. Synonymous variants: 114 observed, 142.23 expected, observed/expected ratio (o/e) 0.8, 90% interval 0.69 to 0.94.
Homologues: Orthologues: chimpanzee SIGLEC11 (31% identical), macaque SIGLEC11 (26% identical), macaque SIGLEC16 (25% identical), mouse Siglecg (21% identical), rat Siglec10 (19% identical), guinea pig Siglec10 (19% identical), tropical clawed frog siglecl2 (14% identical), tropical clawed frog siglecl1 (13% identical), tropical clawed frog siglecl1 (8% identical). Paralogues in human: SIGLEC11 (32% identical), SIGLEC10 (25% identical), CD22 (22% identical), SIGLEC5 (22% identical), SIGLEC14 (19% identical), SIGLEC8 (19% identical), SIGLEC12 (18% identical), SIGLEC7 (18% identical), SIGLEC9 (18% identical), CD33 (15% identical), SIGLEC6 (15% identical), SIGLEC1 (13% identical), and 4 more.
Diseases named in the same sentence as SIGLEC16 in open-access papers:
SIGLEC16 is named in the same sentence as 11 diseases in open-access papers, as found by Europe PMC text mining. Sharing a sentence is not in itself a finding about the gene and the disease. The quoted sentences say what the papers report.
glioma (2 papers, 2021 to 2023). A benign or malignant brain and spinal cord tumor that arises from glial cells (astrocytes, oligodendrocytes, ependymal cells). "If microglia-expressed Siglec-16 is functionally important for human immunity, the polymers of α2,8-linked sialic acids are potentially relevant in the host defense against glioma cells." (PMID 34299113, 2021). "In line with this hypothesis, it is reasonable to target Siglec-16 using modified nanoparticles resulting in the activation of glioma-associated macrophages/microglia and counteracting the protective function of Siglec-11." (PMID 34299113, 2021). "It is interesting, since Siglec-16 has been detected in glioma patients." (PMID 34299113, 2021).
glioblastoma (1 paper, 2024). The most malignant astrocytic tumor (WHO grade IV). "Although in the vast majority of these cases, we do not know how the human-specific changes impact oncogenesis, a positive association with survival in glioblastoma was found for the intact SIGLEC16-positive (activating Siglec) cases." (PMID 38990656, 2024).
gonococcal infection (1 paper, 2019). "The engagement of activating Siglec receptors, such as Siglec‐14 and Siglec‐16, leads to an activation of the pro‐inflammatory signaling cascade that facilitates clearance of gonococcal infection." (PMID 30697344, 2019). "The presence of Siglec‐11 and Siglec‐16 on the cervical columnar epithelium, the main site of gonococcal infection in females, may play a crucial role in host defense." (PMID 30697344, 2019).
mental disorder (1 paper, 2017). A disease that has its basis in the disruption of mental process. "Siglec-16 activates immune and inflammatory responses in the brain microglia, and the activation of brain microglia is associated with mental disorders such as schizophrenia." (PMID 29169316, 2017).
tumor (4 papers, 2020 to 2023). "Similar to that of Siglec-16, the Siglec-15 expression profile was reported to be mutually exclusive to PD-L1 in tumor tissues of non-small cell lung cancer (NSCLC)." (PMID 37234161, 2023). "Even more crucial, though, will be to establish valid systems to study the physiological role of Siglec-16 and its engagement as potentially activating counterpart of Siglec-11 in responses to polySia released under neuroinflammatory conditions, or presented, e.g., on the surface of tumor cells." (PMID 37171513, 2023).
infection (2 papers, 2019 to 2023). The state of being infected such as from the introduction of a foreign agent such as serum, vaccine, antigenic substance or organism. "In fact, Siglec‐14 has been shown to counteract the exploitation of Siglec‐5 by GBS, and Siglec‐16 reduces survival of E. coli K1 during infection." (PMID 30697344, 2019). "It is possible that the greater significance of the Siglec‐16 genotype may result because Siglec‐16 is expressed on macrophages and also on the cervical epithelium, which is the main site of infection." (PMID 30697344, 2019). "Siglec‐16 is expressed by cervical epithelium in addition to immune cells, thus making it an activating Siglec that gonococci are likely to encounter in the early stages of infection." (PMID 30697344, 2019).
SIGLEC16 also shares sentences with these, for which no sentence is quoted: cancer (1 paper); neurodegenerative disease (1); pancreatic adenocarcinoma (1); schizophrenia (1); viral infections (1).